NGF (nerve growth factor)
Diseases named in the same sentence as NGF in open-access papers (continued):
Sharing a sentence is not in itself a finding about the gene and the disease.
Arthritis (35 papers, 2008 to 2025). Inflammation of a joint. "The prevalence of OP increases with the ageing of the population and is associated with an increased risk of fracture and chronic pain, and the targeting of NGF with chelating antibodies ameliorates musculoskeletal pain including back pain and arthritis." (PMID 40860871, 2025). "NGF was elevated in pain and inflammatory diseases including arthritis, and NGF was associated with neuroinflammation and inflammatory pain development." (PMID 39718951, 2025). "Nerve growth factor (NGF) is an important inflammatory mediator implicated in arthritis that binds to its high affinity receptor tropomyosin receptor kinase A (TrkA) and can increase TRPV1 expression." (PMID 30240782, 2018). "Accordingly, the modulation of endogenous NGF levels should be considered as a potential therapeutic target for the management of inflammatory pain associated with arthritis." (PMID 23889761, 2013). "NGF levels are elevated in several conditions associated with pain in humans, including arthritis, cystitis and chronic headaches." (PMID 23889761, 2013). "Earlier this year the FDA Arthritis Advisory Committee met to discuss the anti-NGF class of drugs currently under development, and associated safety issues." (PMID 24170255, 2013). "A pathogenic role for the NGF/trkA-p75 axis and other neurotrophins has been postulated for airway inflammation, atopic dermatitis, psoriasis, inflammatory bowel disease, and arthritis." (PMID 19490633, 2009). "In addition, to characterize the changes in the pain system, other biomarkers should be measured including sensory neuropeptides (i.e., nerve growth factor (NGF)) and mediators along the NF-κB pathway, which have been implicated in chronic inflammatory pain conditions such as arthritis." (PMID 23213513, 2012). "Tanezumab, an emergent NGF-neutralizing antibody, has shown effectiveness against arthritis pain and other symptoms, but its clinical viability is questionable due to marked adverse reactions at high doses and limited effectiveness at lower doses." (PMID 39589893, 2024). "This study aimed to determine the temporal expression patterns of NGF in rat skin (epidermis) during adjuvant-induced arthritis (AIA)." (PMID 38612839, 2024). "This study presents intriguing insights into the temporal expression profile of NGF in rat skin during adjuvant-induced arthritis (AIA)." (PMID 38612839, 2024). "In the context of arthritis, elevated concentrations of nerve growth factor have been observed in synovial fluid." (PMID 38054001, 2023). "We further confirm that SF from arthritis patients have much higher concentration of proNGF than of mature NGF." (PMID 35309353, 2022). "Upregulated levels of NGF and TrkA have been reported in the synovial fluid of some patients with arthritis." (PMID 33806315, 2021). "Despite intermediate setbacks from arthritis therapy, the monoclonal antibodies against NGF are an important contribution of anti-inflammatory options, e.g., for arthritis, but also for low back pain." (PMID 33063247, 2020). "More importantly, macrophage depletion via clodronate liposomes reduces the elevated pro-inflammatory cytokines and NGF and reduces pain behaviors in a model of arthritis." (PMID 31447644, 2019). "In an animal model of arthritis produced by injection of complete Freund’s adjuvant into the knee joint, systemic administration of anti-NGF attenuated nerve fibre sprouting and arthritis pain." (PMID 30155845, 2018). "Targeting of nerve growth factor (NGF) with sequestering antibodies is a promising new direction for the treatment of musculoskeletal pain including back pain and arthritis." (PMID 29922744, 2018). "There is an increase in NGF levels in human pain conditions that are characterized by inflammation, such as arthritis, and NGF applied exogenously to the human skin or muscle produces hyperalgesia or allodynia." (PMID 28955292, 2017).
Arthritis (continued). "The synovial fluids of patients with rheumatoid arthritis are also characterized by an increased concentration of NGF, and its up-regulation in inflamed synovia was confirmed in studies on different animal models of induced arthritis." (PMID 28492466, 2017). "Expression of NGF and the sensory nerve growth it stimulates are believed to link osteochondral angiogenesis to pain in different forms of arthritis including OA." (PMID 24170255, 2013). "TRK-A and its ligand NGF are mediators of inflammatory diseases such as dermatitis, psoriasis, and arthritis." (PMID 24386191, 2013). "Under inflammatory conditions such as allergy and arthritis, NGF can be produced, stored, and released by eosinophils, mast cells, lymphocytes, and synovial fibroblasts, as well as monocytes and macrophages." (PMID 19490633, 2009). "Therefore, nerve growth factor has received widespread attention as a potential therapeutic target for arthritis." (PMID 40860871, 2025). "Different animal models of induced arthritis show increased NGF expression." (PMID 38892241, 2024). "Therefore, in this study, we used TrkA and Rab7 pharmacological inhibitors to block the NGF signaling during adjuvant-induced arthritis (AIA) to determine the effect of NGF on glutaminase (GLS) levels in DRG neurons and pain behavior in AIA animals." (PMID 38892241, 2024). "A previous study found that nerve growth factor (NGF) released from the sprouted sympathetic fibers in the synovial membrane and upper dermis contributed to the pain-related behavior associated with arthritis." (PMID 36910013, 2023). "The reduced expression of TrkA in the immune cells of arthritis patients may hinder the activation of regulatory feedback mechanisms by NGF, thereby contributing to the development and maintenance of chronic inflammation." (PMID 37998739, 2023). "Interestingly, research has demonstrated that pretreatment with NGF-Abs reduces or prevents arthritis induced by carrageenan, indicating a functional role of NGF in this type of peripheral inflammation." (PMID 37998739, 2023). "NGF also contributes to sensory hyperinnervation and hyperalgesia in response to inflammation, and anti-NGF therapy has anti-nociceptive effects in the treatment of arthritis." (PMID 31447644, 2019). "Furthermore, nerve growth factor was also found to co-localize with increased nerve fibers in knee joint degeneration, which contributes to arthritis pain sensation by sensitizing the peripheral nerve endings." (PMID 28469263, 2017). "The TrkA imbalance found in arthritis patients might prevent NGF from activating the regulatory anti-inflammatory feed-back mechanisms, thus contributing to the development and maintenance of chronic inflammation." (PMID 28492466, 2017). "Decreases in TrkA expression, such as that recently demonstrated in immune cells of arthritis patients, might prevent the activation by NGF of regulatory feed-back mechanisms, thus contributing to the development and maintenance of chronic inflammation." (PMID 28492466, 2017). "However, similarities between reductions in pain behaviour in the current study, and findings with agents that block NGF, both in animal models and in man, support the selection of the NGF/TrkA pathway as a target for arthritis pain." (PMID 27145816, 2016). "During inflammation or arthritis, NGF levels rise, and nociceptors consequently become sensitised." (PMID 27145816, 2016). "NGF expression is associated with inflammatory disease activity in RA and NGF/TrkA might contribute to neurogenic inflammation in arthritis by increasing neuronal release of substance P and calcitonin gene-related peptide." (PMID 27145816, 2016). "Increased IL-1β and NGF levels in the synovial fluid are symptoms of arthritis." (PMID 26577823, 2015).
Arthritis (continued). "It has also been shown that there is an acute increase of NGF mRNA within the mast cells infiltrating the inflamed synovial membrane in adjuvant induced arthritis in rats and that the levels remain elevated up to two weeks after arthritis has been induced." (PMID 19014600, 2008). "FLS isolated from patients with arthritis are thus characterized by a high p75NTR and a low TrkA expression that may favor the biological effects of proNGF and dampen the anti-inflammatory actions of mature NGF mediated through TrkA activation." (PMID 35309353, 2022). "Nerve growth factor (NGF) has attracted attention as a master regulator of chronic pain and a molecule that controls arthritis-induced pain." (PMID 38637604, 2024). "In contrast, anti-NGF antibodies are therapeutic agents designed to block NGF’s effects in a controlled manner, without inducing autoimmune reactions, providing relief from pain and inflammation in conditions like arthritis." (PMID 37998739, 2023). "NGF not only regulates the proliferation and differentiation of bone neoplasms, osteodynia, and chondrocytes through activation of its high-affinity receptor TrkA, which affects the PI3K, Ras, and PLC pathways, but also helps to slow the progression of arthritis." (PMID 40860871, 2025). "However, due to the pleiotropic nature of NGF action, the effect of inhibiting NGF-TrkA signalling in arthritis treatment remains controversial, and it is not clear whether there are significant negative effects." (PMID 40860871, 2025).
peripheral nerve injury (34 papers, 2009 to 2025). Injury to a peripheral nerve. "The observed improvements, potentially mediated by its antioxidant and anti-inflammatory properties and increased NGF expression, suggest its potential as a therapeutic agent for peripheral nerve injuries." (PMID 41168281, 2025). "Restoring NGF levels and axonal parameters through liraglutide administration substantiates its potential as a therapeutic intervention for peripheral nerve injuries." (PMID 38248323, 2024). "Studies have demonstrated that the early inhibition of NGF and its surface receptor tropomyosin receptor kinase A (TrkA) after peripheral nerve injury can decrease the formation of painful neuromas and alleviate the pain caused by them." (PMID 38672500, 2024). "As a neurotrophic factor regulating neuronal cell survival, proliferation, and differentiation after peripheral nerve injury, the abnormal secretion of NGF at the injury site also plays a crucial role in the formation of painful neuroma and hyperalgesia." (PMID 38672500, 2024). "It has been reported that nerve growth factor (NGF) can activate SC autophagy in peripheral nerve injury, so we next studied the relationship between PanCa-related NGF and SC autophagy." (PMID 35109895, 2022). "Comparing Groups C to A and B, the improved functional recovery and the potential reparative role of the anti-inflammatory DS and neurotrophic NGF in the treatment of peripheral nerve injuries was noted." (PMID 34768986, 2021). "After peripheral nerve injury, NGF, BDNF, and NT3 are secreted and bind their high-affinity receptors trkA, trkB, and trkC and, then, activate the tyrosine kinase signaling system." (PMID 33447879, 2021). "The developmental and adult neurobiology of nerve‐growth factor (NGF) are well investigated, and mouse (m)NGF has been used to promote recovery following peripheral nerve injury." (PMID 33043628, 2021). "Peripheral nerve injury is accompanied by a reduction in NGF retrograde transport and a dramatic decrease in sympathetic neuron activity and cholinergic synapses within the ganglia." (PMID 32017764, 2020). "Preclinical studies have shown that levels of NGF are increased in preclinical models of inflammation and peripheral nerve injury." (PMID 33338083, 2020). "In this work, we use PDAPEI polycation to condense VEGF and NGF for the treatment of peripheral nerve injury." (PMID 32169062, 2020). "Intrathecal administration of NGF restored the effectiveness of morphine in attenuating hyperalgesia following peripheral nerve injury." (PMID 28626808, 2017). "In brief, the experimental data increase the feasibility of translation to clinical trials using NGF–CMSs as neurotrophic support for peripheral nerve injury." (PMID 24983464, 2014). "The laminin binding NGF targeted to the nerve extracellular matrix laminin and promoted the repair of peripheral nerve injuries." (PMID 19587785, 2009). "The thermally adjustable viscosity of GS facilitated the fast creation of a 3D gradient and a linear arrangement of NGF@MPs, resulting in magnetically regulated 3D gradient release of NGF to improve topographical nerve guidance and wound healing in peripheral nerve injuries." (PMID 40047623, 2025). "Our studies thus provide strong support that NGF may serve as a powerful pharmacological therapy for peripheral nerve injuries." (PMID 32042328, 2020). "Previous studies on Slit focusing on SCs suggested that peripheral nerve injury could lead to the expression of various neurotrophic factors in SCs, including NGF, BDNF, neurotrophin 4/5, insulin growth factor 1 and 2, and Slit2 and Slit3." (PMID 31607866, 2019). "At present, in vivo and in vitro studies have demonstrated the synergistic effect of FK506 and NGF in the treatment of peripheral nerve injuries; however, it remains unclear whether this effect is present in the treatment of spinal cord injury." (PMID 24137280, 2013).
peripheral nerve injury (continued). "Previous studies have shown that FK506 and NGF exhibit a synergistic effect in the treatment of peripheral nerve injury; however, it remains unclear whether the synergistic effect is present in the treatment of spinal cord injury." (PMID 24137280, 2013). "After peripheral nerve injury (PNI), growth factors, such as NGF, play an important role in promoting cell growth and survival, axon and myelin sheath regeneration, cell differentiation, and angiogenesis." (PMID 41228660, 2025). "After peripheral nerve injury, several neurotrophic factors, such as BDNF, GDNF, NGF, and neurotrophin-3, are synthesized and secreted by SCs to promote neuroregeneration." (PMID 37071193, 2023). "Additionally, administration of exogenous NGF could activate autophagy in dedifferentiated SCs, accelerate the clearance and phagocytosis of myelin debris, and promote the regeneration of axons and myelin sheath in the early stage of peripheral nerve injury." (PMID 35690849, 2022). "Through the VDR, Vitamin D can upregulate nerve growth factor (NGF), and in a rat model of peripheral nerve injury, rats exposed to vitamin D2 demonstrated significantly increased axogenesis and axon diameters." (PMID 32536905, 2020). "Major neurotrophic factors, such as IGF1, IGF2, NGF, BDNF, NT-3, and NT-4/5 can be produced by macrophages and are greatly upregulated in peripheral nerve injury, often concurrent with the influx of macrophages." (PMID 29907154, 2018). "Nerve growth factor (NGF) may activate the autophagy of SCs, which is crucial for degradation and clearance of myelin debris following peripheral nerve injury via the p75NTR/AMPK/mTOR axis." (PMID 35109895, 2022). "In China, mouse (m)NGF has been used clinically to treat peripheral nerve injury, but there have been no reports of its ability to promote nerve regeneration after free perforator flap procedures." (PMID 33043628, 2021). "CMNPs orally administrated treatment had beneficial effects on the rehabilitation of peripheral nerve injuries regarding all studied parameters: SFI score, pain-like behavior measurement, body weight dynamic evolution, serum NGF levels, and histological-ultrastructural studies." (PMID 33946445, 2021). "Therefore, various neurotrophic factors, such as NGF, BDNF, and GDNF, have been used to enhance the repair outcomes of peripheral nerve injury." (PMID 33838005, 2021). "GDNF and NGF are two major neurotrophins that are significantly more effective than other growth factors in promoting axonal regeneration, and a synergistic effect of NGF and GDNF was observed in the treatment of peripheral nerve injury." (PMID 34955758, 2021). "The nerve growth factor (NGF), which plays a major role in the development and maintenance of neuropathic pain following peripheral nerve injury has been proven to up-regulate TRPV1 receptor and be involved in the phenotypic changes which lead to the development of neuropathic pain." (PMID 20937102, 2010). "Nerve growth factor (NGF), glial cell line-derived neurotrophic factor (GDNF), brain derived neurotrophic factor (BDNF) and neurotrophin-3 (NT-3) have all been added to biomaterials to treat TBI as well as neurodegenerative disorders spinal cord injuries and peripheral nerve injuries." (PMID 26056586, 2014).